PRELP (proline and arginine rich end leucine rich repeat protein)
Description:
May anchor basement membranes to the underlying connective tissue.
Synonyms: SLRR2A; prolargin; MST161; MSTP161
Tractability: Antibody: its Gene Ontology location is reachable by antibodies, with high confidence; UniProt places it where antibodies can reach, with medium confidence; UniProt predicts a signal peptide or a membrane-spanning region.
Gene: Protein-coding gene on chromosome 1 (203,475,777 to 203,491,352, forward strand). Ensembl gene ENSG00000188783.
Subcellular location: Secreted, extracellular space, extracellular matrix
Subcellular location (Human Protein Atlas): Endoplasmic reticulum; Plasma membrane; Predicted to be secreted
Pathways (Reactome):
Disease: Defective B4GALT1 causes B4GALT1-CDG (CDG-2d); Defective CHST6 causes MCDC1; Defective ST3GAL3 causes MCT12 and EIEE15
Metabolism: Keratan sulfate biosynthesis; Keratan sulfate degradation
Gene Ontology:
Molecular function: extracellular matrix structural constituent; extracellular matrix structural constituent conferring compression resistance; heparin binding
Biological process: skeletal system development
Cellular component: extracellular exosome; extracellular matrix; extracellular region; extracellular vesicle; gel phase of interstitial matrix; Golgi lumen; lysosomal lumen
Genetic constraint (gnomAD): Loss-of-function variants: 16 observed, 23 expected, observed/expected ratio (o/e) 0.7, 90% interval 0.47 to 1.06. The upper end of that interval is the gene's LOEUF score, 1.06, which puts it in group 4 of 6, group 1 being the genes least tolerant of losing a copy. Missense variants: 433 observed, 506.81 expected, observed/expected ratio (o/e) 0.85, 90% interval 0.79 to 0.93. Synonymous variants: 233 observed, 221.93 expected, observed/expected ratio (o/e) 1.05, 90% interval 0.94 to 1.17.
Homologues: Orthologues: chimpanzee PRELP (100% identical), macaque PRELP (98% identical), pig PRELP (93% identical), dog PRELP (92% identical), rabbit PRELP (90% identical), guinea pig PRELP (90% identical), mouse Prelp (90% identical), rat Prelp (90% identical), tropical clawed frog prelp (65% identical), zebrafish prelp (57% identical). Paralogues in human: KERA (48% identical), FMOD (37% identical), OMD (36% identical), LUM (35% identical), ECM2 (29% identical), LINGO3 (20% identical), OMG (19% identical), LINGO4 (18% identical), EPYC (18% identical), OGN (16% identical).
Diseases named in the same sentence as PRELP in open-access papers:
PRELP is named in the same sentence as 62 diseases in open-access papers, as found by Europe PMC text mining. Sharing a sentence is not in itself a finding about the gene and the disease. The quoted sentences say what the papers report.
bladder cancer (7 papers, 2021 to 2025). "We revealed that loss of PRELP is an important prerequisite for bladder cancer onset using PRELP−/− mouse." (PMID 36230849, 2022). "Although PRELP has been found to be a tumor suppressor in hepatic cancer 38, bladder cancer 39 and retinoblastoma 40, its role in colorectal cancer is unclear." (PMID 39247594, 2024). "Given that PRELP play a role in tumor inhibition in hepatic cancer 38, bladder cancer 39 and retinoblastoma 40, the exact role of PRELP in CRC is not clear." (PMID 39247594, 2024). "We previously demonstrated the cell-cell junction dysfunction in response to the OMD and PRELP expression levels in bladder cancer cells using electron microscope analysis along with immunofluorescence analysis." (PMID 37936982, 2023). "Intriguingly, PRELP expression was regulated by epigenetically through acetylation of lysine residue 5 of histone H2B in the PRELP gene promoter region in bladder cancer." (PMID 37936982, 2023). "We previously demonstrated that OMD and PRELP are both expressed in umbrella bladder epithelial cells and involved in bladder cancer initiation in a partially redundant manner." (PMID 37936982, 2023). "Although we showed that chromosome 9q deletion, which is involved in the development of bladder cancer, is responsible for the loss of function of the OMD gene, the mechanism of PRELP gene repression remains unresolved." (PMID 36371227, 2022). "TGF-β pathway and growth factor pathways are inhibited by PRELP as observed in biochemical analysis on bladder cancer cells." (PMID 36230849, 2022). "In this study, we showed that PRELP gene repression is relieved by HDACi mediated by histone acetylation in bladder cancer cells." (PMID 36371227, 2022). "Our observations suggest that suppression of PRELP potentiates RB progression through EMT mechanisms, especially those associated with cell adhesion, as observed in bladder cancer." (PMID 36230849, 2022). "Here, we show that repression of PRELP mRNA expression in bladder cancer cells is alleviated by HDAC inhibitors (HDACi) through histone acetylation." (PMID 36371227, 2022). "HDAC inhibitors show anti-cancer effects by partially regulating the function of PRELP in bladder cancer." (PMID 36556220, 2022). "More recently, PRELP and osteomodulin, a most highly conserved SLRP member with PRELP, have been also found that they regulate bladder cancer initiation in a functionally partially redundant manner." (PMID 33428936, 2021). "Although PRELP is an important factor in the development and progression of bladder cancer, the mechanism of PRELP gene repression remains unclear." (PMID 36371227, 2022). "In addition, recent studies have indicated that PRELP has functions as a tumor-suppressing protein inhibiting the progression of bladder cancer and hepatocellular carcinoma." (PMID 33428936, 2021). "Next, we used two bladder cancer cell lines, RT4 and J82 to investigate the relationship between histone modification and repression of PRELP gene expression." (PMID 36371227, 2022). "The fact that PRELP expression does not affect the expression levels of HDAC1, 2 is consistent with the view that the PRELP gene is activated following acetylation of H2BK5 and orchestrates the EMT program in bladder cancer cells." (PMID 36371227, 2022). "In this sense, it has been revealed that PRELP interacts with TGFβ1, leading to the suppression of canonical SMAD signal transduction and suggested that PRELP suppresses bladder cancer progression by reversing the epithelial-mesenchymal transition through inhibition of TGFβ1 signaling pathway." (PMID 40634432, 2025). "Although H2BK5 acetylation was increased in the protein as a whole following SAHA treatment, our results indicate that repression of PRELP gene expression involves deacetylation of H2BK5ac in the promoter region, and SAHA treatment reverses the repression via H2BK5ac in bladder cancer cells." (PMID 36371227, 2022).
hepatocellular carcinoma (5 papers, 2020 to 2023). A malignant tumor that arises from hepatocytes. "In accordance with recently published results for hepatocellular carcinoma, PRELP overexpression inhibited cell proliferation, migration and invasion of murine and human melanoma cell lines." (PMID 37730606, 2023). "The overexpression of PRELP correlates with better patient survival and inhibits both cell proliferation and migration in hepatocellular carcinoma." (PMID 36556220, 2022). "In support of this hypothesis, previous studies showed that PRELP is localized in the nucleus as well as cytoplasm of hepatocellular carcinoma tissues, and the N-terminal peptide of PRELP is also translocated to the nucleus where it inhibits the DNA-binding activity of NF-κB." (PMID 33428936, 2021). "The inhibitory effect of PRELP on proliferation was recently shown for hepatocellular carcinoma cells but otherwise its biological function is not well known." (PMID 34074003, 2021).
breast carcinoma (4 papers, 2015 to 2024). "A peptide corresponding to the N-terminal heparin-binding domain of PRELP inhibits osteoclastogenesis in breast cancer metastases." (PMID 36556220, 2022).
melanoma (4 papers, 2023 to 2025). A malignant, usually aggressive tumor composed of atypical, neoplastic melanocytes. "Only 2/48 melanoma cell lines express high PRELP mRNA levels, but the underlying mechanism of the lack of PRELP expression has not yet been determined." (PMID 37730606, 2023). "Since upregulation of PRELP has been demonstrated to be associated with anti-tumoral activity, PRELP should be reconstituted in melanoma, which might be a novel form of anti-cancer strategy." (PMID 37730606, 2023). "Concerning the underlying molecular mechanisms leading to PRELP downregulation, genomic abnormalities in PRELP, such as mutations and deletions, were only found at a low frequency (7%) suggesting deregulation as a major mechanism of impaired PRELP expression in melanoma." (PMID 37730606, 2023). "Not only BGN, but also PRELP has a positive immune modulatory potential by increasing the expression of HLA class I APM and IFN-γ signaling components suggesting a tumor suppressive activity of PRELP in melanoma." (PMID 37730606, 2023). "Since no information exists for skin cancer, we investigated the expression, function and clinical relevance of PRELP in melanoma." (PMID 37730606, 2023). "The data from melanoma lesions were in line with a strong downregulation of MHC class I surface expression in murine and human melanoma cells, which exhibit low to marginal PRELP expression (PRELPlow/neg) in 46/48 melanoma cell lines analyzed." (PMID 37730606, 2023). "Based on these data, the effect of PRELP overexpression on CCL5 secretion in Buf1088 melanoma cells was determined using the ELISA." (PMID 37730606, 2023). "Transfection of PRELP into melanoma cell lines restored MHC class I surface expression due to transcriptional upregulation of major MHC class I APM and IFN-γ pathway components." (PMID 37730606, 2023). "Although the ECM has been linked to several hallmarks of cancer, little information is available regarding the expression and function of the ECM protein purine-arginine-rich and leucine-rich protein (PRELP) in cancer, including melanoma." (PMID 37730606, 2023). "Many of these downregulated proteomic cargoes in melanoma sEVs, including collagens (COL1A1, COL3A1, COL6A1–A3, and COL14A1), matrix-associated proteoglycans (DCN, LUM, FMOD, OGN, and PRELP), and structural regulators (TNXB and PCOLCE), are key components of ECM organization and tensile strength." (PMID 41271007, 2025). "Recent studies have found that PRELP could affect tumor immunogenicity in melanoma by up-regulating MHC Class I surface expression, thereby inhibiting tumor development and enhancing CD8 T cell infiltration, which was consistent with our findings." (PMID 39507711, 2024). "Marginal to low PRELP expression levels were found in the 47/49 human melanoma cell lines analysis." (PMID 37730606, 2023). "However, PRELP is heterogeneously expressed in melanoma lesions leading to the assignment of PRELPlow and PRELPhigh melanoma." (PMID 37730606, 2023). "Thus, a link between high PRELP expression levels and increased immunogenicity of melanoma cells is shown in vitro and in vivo." (PMID 37730606, 2023). "In addition, a high frequency of intra-tumoral T cells directly correlated with the expression of MHC class I and PRELP as well as the T cell attractant CCL5 in melanoma lesions." (PMID 37730606, 2023). "Kaplan–Meier analysis revealed that PRELP expression levels correlated with the overall survival (OS) of melanoma patients with a reduced patients’ survival rate (HR = − 0.2635; p = 0.0121) in PRELPlow melanoma lesions." (PMID 37730606, 2023). "Since proliferation, invasion and metastasis formation are significant features of melanoma, the effect of PRELP overexpression on growth properties was analyzed, which might also lead to identifying novel therapeutic targets controlling disease progression." (PMID 37730606, 2023).
melanoma (continued). "Vice versa, reduced PRELP expression in melanoma cells is associated with low expression levels of MHC class I APM components and members of the IFN-γ signal transduction as well as CCL5, which could be reconstituted by PRELP overexpression." (PMID 37730606, 2023). "However, the underlying mechanisms of PRELP expression in 2/48 melanoma cell lines have not been identified." (PMID 37730606, 2023). "However, the inhibitory role of PRELP on melanoma growth has to be investigated in more detail and might be associated with the modulation of multiple signal transduction pathways, such as β-catenin or NF-KB signaling." (PMID 37730606, 2023). "In addition, 48 melanoma cell lines were tested for PRELP mRNA expression using qRT-PCR." (PMID 37730606, 2023). "PRELP expression was generally downregulated in all solid cancers (log2FC = − 0.758 and p < 0.001), but there exist tumor-dependent differences in the extent of downregulation, which was more pronounced in melanoma (log2FC = − 1.583 and p < 0.001) when compared to corresponding normal tissues." (PMID 37730606, 2023). "In addition, high PRELP expression is significantly correlated with increased patients’ survival and CD8+ T cell infiltration, which might be associated with enhanced T cell responses in melanoma." (PMID 37730606, 2023). "Therefore, PRELP might serve as a marker for predicting disease progression and its recovery could revert the tumorigenic phenotype, which represents a novel therapeutic option for melanoma." (PMID 37730606, 2023). "Furthermore, bioinformatics analyses of high throughput TCGA and GEO data showed a reduced PRELP expression occurring at a high frequency in solid cancers compared to adjacent normal tissues, including primary melanoma lesions, which was even more pronounced in melanoma metastases." (PMID 37730606, 2023). "Since genetic alterations were not identified, the impaired PRELP expression in melanoma might be mainly due to its deregulation rather than structural abnormalities." (PMID 37730606, 2023). "In addition, PRELP overexpression is accompanied by high CCL5 secretion levels in cell supernatant, an impaired TGF-β signaling as well as a reduced cell proliferation, migration and invasion of melanoma cells." (PMID 37730606, 2023). "Based on these bioinformatics data, it was hypothesized that the low PRELP expression levels in melanoma might be mainly due to deregulation rather than genomic abnormalities." (PMID 37730606, 2023). "Therefore, PRELP is a prognostic biomarker and might be a potential (immune) therapeutics for enhancing CD8+ T cell responses, thereby leading to novel approaches for the treatment of melanoma patients." (PMID 37730606, 2023). "Indeed, our results demonstrated a PRELP-mediated induction of the expression of MHC class I and secretion of CCL5 in melanoma cells, which might contribute (i) to the recruitment of effector T cells into the tumor tissues and (ii) to an increased recognition by CD8+ T cells." (PMID 37730606, 2023).
retinoblastoma (4 papers, 2022 to 2024). A malignant tumor that originates in the nuclear layer of the retina. "Recently, we reported that PRELP regulates cell-cell adhesion of bladder umbrella epithelial cells and retinoblastoma cells through pEMT." (PMID 37936982, 2023). "Here, we found that expression of proline/arginine-rich end leucine-rich repeat protein (PRELP) is strongly downregulated in human retinoblastoma and highly expressed in Müller glial cells in normal retina." (PMID 36230849, 2022). "We previously discovered the downregulation of PRELP in many different cancers, including retinoblastoma." (PMID 36230849, 2022). "On the other hand, application of PRELP protein to retinoblastoma cell lines enhances cell–cell and cell–substrate adhesion and inhibits anchorage independent growth by reversing EMT." (PMID 36230849, 2022). "Recently, we demonstrated that PRELP has the ability to activate mesenchymal-to-epithelial transition (MET), resulting in the enhancement in bladder epithelial cell-cell and retinoblastoma cells." (PMID 37936982, 2023).
chronic lymphocytic leukemia (3 papers, 2013 to 2023). "While overexpression of PRELP has been reported to have tumor suppressive activity in solid tumors characterized by a reduced invasion, anchorage-independent growth, metastasis formation and tumorgenicity, PRELP expression is involved in the pathobiology of chronic lymphocytic leukemia." (PMID 37730606, 2023). "By glycosylation, PRELP could transform into a 38 kDa core protein which was specifically expressed in chronic lymphocytic leukemia (CLL) cells." (PMID 33033521, 2020).
colorectal cancer (3 papers, 2024 to 2025). A primary or metastatic malignant neoplasm that affects the colon or rectum. "This suggests that PRELP+ CAFs are associated with advanced colorectal cancer and may contribute to metastasis." (PMID 41031085, 2025). "It has been shown that all of these risk genes, except PRELP, are related to colorectal cancer." (PMID 39247594, 2024). "Furthermore, PRELP is linked to the onset, progression, and metastasis of colorectal cancer, suggesting it may act as a promoter in cancer progression and could be a potential therapeutic target or prognostic marker." (PMID 39968416, 2025). "As PRELP+ CAFs represent the terminal differentiation state of fibroblasts in colorectal cancer liver metastases, we sought to identify the transcription factors (TFs) driving their distinct phenotype." (PMID 41031085, 2025). "This enrichment pattern implies that PRELP+ CAFs may contribute to the aggressive phenotype characteristic of MSS colorectal cancers." (PMID 41031085, 2025). "Using the top 10 upregulated genes as a signature for PRELP+ CAFs, we calculated GSVA score for patients in the TCGA colorectal cancer cohort." (PMID 41031085, 2025).
cardiomyopathies (2 papers, 2022 to 2023). "One example of a discordant ECM protein was PRELP, which was also identified as a druggable gene that was decreased in fibroblasts in all three cardiomyopathies." (PMID 36790929, 2023). "Among the identified three genes of DCM with HF, NPPA has already been known to involved in cardiomyopathies, while reports on OMD and PRELP are limited." (PMID 36544902, 2022).
endometriosis (2 papers, 2017 to 2020). The growth of functional endometrial tissue in anatomic sites outside the uterine body. "The ID2 gene expression was increased in the most advanced stage of endometriosis and in ovarian endometriomas, the PRELP was more expressed in peritoneal lesions, and the SMOC2 was highly expressed in both peritoneal and endometrioma lesions." (PMID 28678915, 2017). "Interestingly, PRELP has been demonstrated to be upregulated in patients with endometriosis." (PMID 32112646, 2020). "Additionally, the expression of ID2, PRELP and SMOC2 genes is similar between the normal endometrium and the eutopic endometrium of women with endometriosis." (PMID 28678915, 2017). "In the current study, we compared the expression of the ID2, PRELP and SMOC2 genes in endometriotic lesions (ovarian and peritoneal) and in the eutopic endometrium of women with and without endometriosis in the proliferative phase of their menstrual cycle." (PMID 28678915, 2017). "The expression of the ID2, PRELP and SMOC2 genes was compared between the endometrium of women without endometriosis in the proliferative phase of their menstrual cycle and the eutopic and ectopic endometrium of women with endometriosis in the proliferative phase." (PMID 28678915, 2017).
Hutchinson-Gilford progeria (2 papers, 2025). "Notably, PRELP, potentially associated with Hutchinson-Gilford progeria, was also downregulated in rhPDGF-AB/BB-treated AF cells." (PMID 40668091, 2025). "Moreover, according to the literature, the expression of PRELP coincides with the appearance of a premature-aging disease symptoms, called HGPS (Hutchinson-Gilford Progeria Syndrome)." (PMID 41083899, 2025).